TILAM (TGF-beta induced lncRNA activating myofibroblasts)
Synonyms: formerly LINC01969
Gene: Long non-coding RNA gene on chromosome 17 (50,199,876 to 50,215,922, forward strand). Ensembl gene ENSG00000249406.
Diseases named in the same sentence as TILAM in open-access papers:
TILAM is named in the same sentence as 2 diseases in open-access papers, as found by Europe PMC text mining. Sharing a sentence is not in itself a finding about the gene and the disease.
TILAM shares sentences with these, for which no sentence is quoted: cancer (1 paper); tumor (1).